U3 (Small nucleolar RNA U3 )
Synonyms: LOC124903594
Gene: Small nucleolar RNA gene on chromosome 15 (69,457,941 to 69,458,149, reverse strand). Ensembl gene ENSG00000207119.
Gene Ontology:
Biological process: RNA processing
Cellular component: nucleolus
Homologues: Orthologues: macaque U3 (93% identical), mouse Snord3b1 (76% identical), mouse Snord3b2 (76% identical), mouse Snord3b3 (76% identical), mouse Snord3b4 (76% identical), rat LOC120095492 (74% identical), mouse Snord3a (73% identical). Paralogues in human: U3 (79% identical), U3 (78% identical), SNORD3G (78% identical), SNORD3P1 (77% identical), SNORD3E (77% identical), U3 (76% identical), U3 (75% identical), SNORD3D (75% identical), SNORD3H (75% identical), U3 (74% identical), U3 (73% identical), U3 (72% identical), and 13 more.